TBK1 (TANK binding kinase 1)
Diseases named in the same sentence as TBK1 in open-access papers (continued):
Sharing a sentence is not in itself a finding about the gene and the disease.
viral infection (continued). "Together, these data show that viral infection can prevent lysosomal degradation of ZNF268a in a TBK1-dependent manner." (PMID 37926288, 2023). "As one of the DNA sensors, interferon (IFN)-γ inducible protein 16 (IFI16) play a major role in response to virus infections through activating the canonical STING/TBK-1/IRF3 signaling pathway." (PMID 37410794, 2023). "Upon viral infection, the upregulation of miR-200b-3p led to the reduction of TBK1-mediated IFN-I production and impaired the antiviral innate response." (PMID 37222520, 2023). "Negative regulator like NEDD4 specifically promotes the degradation of activated phospho-TBK1 (p-TBK1) after viral infection." (PMID 37352355, 2023). "To systemically elucidate how ZNF268a regulates the TBK1 signaling complex, we performed mass spectrometry to identify potential ZNF268a interacting partners during viral infection." (PMID 37926288, 2023). "The transcriptional levels of TBK1 are stimulated by viral infection at 9 h post-infection and subsequently allow the accumulation of IRF3 and NF-κB transcripts." (PMID 37764935, 2023). "Upon viral infection, TBK1 interacts with cytosolic ZNF268a to catalyze the phosphorylation of Serine 178 of ZNF268a, which prevents the degradation of ZNF268a, resulting in the stabilization and accumulation of ZNF268a in the cytoplasm." (PMID 37926288, 2023). "Since TBK1 is a critical kinase required for the induction of type I IFNs and subsequent cellular antiviral responses, its activity must be regulated during viral infection for immune hemostasis." (PMID 35632751, 2022). "We used a mouse model of viral pancreatitis for our studies to explore the effect of TBK1 inhibition on CVB infection because the pancreas is an early target for viral infection during acute infection." (PMID 36044516, 2022). "K241 acetylation during the early stage of viral infection enhances the recruitment of IRF3 to TBK1." (PMID 35395857, 2022). "As such, it is suggested that GSNOR prevents S-nitrosylation of TBK1, thereby preserving the immune-activating functions of TBK1 amid viral infection." (PMID 35395857, 2022). "For example, the E3 ubiquitin ligases TRIM56 and TRIM32 catalyze the K63-linked ubiquitination of STING upon viral infection, thereby promoting STING recruitment and STING dimerization by TBK1." (PMID 35992663, 2022). "Upon viral infections, IκB kinase-related kinases TBK1 and IKKε activate the transcription factors such as IRF3 and IRF7, resulting in IFN-β production." (PMID 39290965, 2022). "During viral infection, K63-linked polyubiquitination of TRAF3 recruits TBK1-IKKε, and IRF3 is then activated to trigger type I IFN production." (PMID 36056146, 2022). "Following virus infection, TBK1 phosphorylates IRF7, resulting in IRF7 dimerization and migration to the nucleus, where it binds to the IFN-β promoter." (PMID 36366509, 2022). "TBK1 plays a significant role in the innate immune response and is used in vaccine research, such as the small molecule inhibitor of TBK1, which can be used as an adjuvant for yellow fever vaccine." (PMID 35129065, 2022). "Its mediated IFN gene stimulating factor (STING)- TANK-binding kinase 1 (TBK1)-IRF3-IFN pathway is a central cellular host defense against viral infection." (PMID 36090998, 2022). "By illuminating new avenues of investigation, therapeutic strategies targeting IRF7 or TBK-1 can be developed to boost vaccine responses to viral infections such as influenza and SARS-CoV-2 to alleviate substandard vaccine outcomes in the older population." (PMID 35849213, 2022). "Typically, viral infection activates TBK1, which leads to type 1 IFN signalling after IRF3 (IFN regulatory factor 3) phosphorylation, but abnormal production of type 1 IFN can lead to autoimmune disorders, as a result of aberrant immune responses." (PMID 35204725, 2022).
viral infection (continued). "We found that at 24 hours (h) post-infection (p.i.), TBK1-/- MEFs displayed increased viral infection compared to TBK1+/+ and TBK1+/- MEFs, as evidenced by eGFP-expressing cells (10% increase; *, p < 0.05)." (PMID 36044516, 2022). "Upon viral infection, cellular TBK1- and IKKi-mediated Ser385 and Ser386 phosphorylation of IRF3 and the Ser/Thr cluster between amino acids 396 and 405 of IRF3 leads to its conformational change and activation." (PMID 35196784, 2022). "SEC5 (also known as EXOC2) is a component of the exocyst complex and is involved in tank-binding kinase 1 (TBK1)-dependent type I interferon innate immune responses against viral infections." (PMID 36313547, 2022). "This highlights the role of TBK1 in interferon pathway regulation during viral infection in ducks and chickens." (PMID 35632751, 2022). "Third, phosphorylation of IRF3Y107 by SRC was important for IRF3 association with TBK1 and its self-association, as well as induction of IFN-β upon viral infection." (PMID 35468896, 2022). "Given that TMEM33 reduces the TBK1 kinase activity and fish TBK1 plays a vital role in defending against virus infections, the modulation of TMEM33 regulation of the TBK1-mediated cellular antiviral immune response was evaluated." (PMID 33600488, 2021). "TBK1 is one of the major genes involved in predisposition to Amyotrophic Lateral sclerosis and frontotemporal dementia, and one may expect that therapeutic modulation of TBK1-related pathways will be a future challenge in such indications and, more specifically, in viral infections and sarcoidosis." (PMID 34440765, 2021). "Overall, these data indicated that TAP1 affected viral infections by regulating the TBK1/IRF3 signal pathway." (PMID 33925089, 2021). "With regard to TLR signaling, there are striking parallels between PPM1B and PPM1A: Upon viral infection, PPM1B blocks the antiviral response by increased association with and dephosphorylation of TBK1 at Ser-172, allowing enhanced virus replication." (PMID 33882943, 2021). "We found that viral infection induced S-nitrosation of TBK1 in WT cells and the degree of TBK1 S-nitrosation was further increased by GSNOR KO." (PMID 34678655, 2021). "Upon virus infection, activated TBK1 phosphorylates IRF3 and triggers its nuclear translocation, which ultimately promotes the production of type I IFNs and ISGs." (PMID 34882534, 2021). "Since production of type I IFNs is fundamental in controlling viral infections, many viruses have evolved evasion strategies, among these TBK1 modulation, to combat the innate immune mechanisms." (PMID 34634939, 2021). "Several deubiquitinating enzymes and E3 ubiquitin ligases have been shown to regulate the ubiquitin level of TBK1 and participate in innate immune response during virus infection." (PMID 34084167, 2021). "Upon phosphorylation by TBK1, dimerization and nuclear translocation, it drives the expression of several types of IFNs and ISGs that play key roles in the response to viral infection, its control and elimination." (PMID 34696416, 2021). "Following virus infection, USP38 is recruited to the activated TBK1 by NLRP4 and removes K33-linked ubiquitin from K670, which enables K48-ubiquitination by DTX4 and TRIF." (PMID 33808506, 2021). "Here, we present the crosstalk of mTOR and RLR-signaling pathways by demonstrating the requirement of TFG for the interaction of TRAF3 and TBK1 with mTOR upon viral infection." (PMID 33411856, 2021). "The acetylation of TBK1 at Lys241 during the early stage of viral infection enhanced the recruitment of IRF3 to TBK1." (PMID 32772249, 2021). "During virus infection, Lck/Hck/Fgr can directly phosphorylate TBK1 at Tyr354/394 to restrain TBK1 dimerization and activation as a feedback approach in antiviral immunity." (PMID 34966372, 2021). "All these results showed that GSNOR strengthened the antiviral innate immune response by preserving TBK1 activity in response to viral infection." (PMID 34678655, 2021).
viral infection (continued). "Mechanistically, after viral infection, ASB8 interacts with TBK1/IKKi kinase complex and promotes the K48-linked ubiquitination of TBK1/IKKi, which is degraded by proteasome afterward." (PMID 34966372, 2021). "Our results detail the functional role of TFG in innate immunity as an ER-to-Golgi resident protein which allows TRAF3 to interact with upstream adapter protein MAVS and downstream kinase TBK1 resulting in activation of TBK1 upon viral infection." (PMID 33411856, 2021). "Next, we tested the effect of LPS on the phosphorylation profile of NFκB, ERK1/2, JNK, TBK1 and Stat1 when applied 24 h after virus infection." (PMID 34975859, 2021). "To assess changes in RIG-I and MDA5-mediated signaling cascades upon viral infection, we analyzed changes in the phosphorylation of TBK1 and IRF3, which are the downstream events of MAVS activation and hall marker of interferon pathway activation." (PMID 34016972, 2021). "To determine why GSNOR regulates innate immunity via TBK1 activity, we first examined the effects of viral infection on TBK1 S-nitrosation in WT and Gsnor KO L929 cells." (PMID 34678655, 2021). "Results showed that the levels of p-TBK1 and p-IRF3 were reduced in GSNOR-deficient cells compared to WT cells after viral infection." (PMID 34678655, 2021). "As a member of the IκB kinase (IKK) family, TBK1 regulates inflammatory cytokines expression and plays an important role in regulating immune responses induced by bacterial and viral infections." (PMID 33718475, 2021). "For RNA viruses, the major sensors RIG-I and MDA5 bind the adaptor molecule IPS1 upon virus infection, which activates TBK1 and IKKε, resulting in IRF-3 phosphorylation." (PMID 34335514, 2021). "To this end, we examined the ability of TRAF3 to interact with both MAVS and TBK1 upon viral infection in HEK293T cells in which endogenous TFG was knocked down with a TFG-specific short interfering RNA (siRNA, siTFG)." (PMID 33411856, 2021). "Upon virus infection, K63-linked polyubiquitination of TRAF3 leads to the recruitment of TBK1 and the subsequent activation of IRF3 (54, –, 56)." (PMID 33975961, 2021). "As a node protein regulating multiple signaling pathways, TBK1 plays a critical role in various immunopathological events, especially in innate immune responses to bacterial and viral infections." (PMID 34908452, 2021). "Phosphorylation of IRF3 and TBK1 is the hallmark of their activation, which is essential for type I IFN induction during viral infection." (PMID 34950606, 2021). "Similar to mammals, increasing evidence have shown that TBK1 in fish also participate in regulating IRF3-mediated IFN signaling pathway in response to virus infection." (PMID 33584728, 2020). "For example, viral infection induces the expression of the E3 ligase TRIM21, which binds MAVS to promote its K27-linked polyubiquitination at lysine 325 and its association with TBK1." (PMID 32117959, 2020). "GPATCH3 binding to MAVS prevents the assembly of the MAVS/TRAF6/TBK1 complex during viral infection." (PMID 32536927, 2020). "Stimulatory phosphorylations were identified by LC-MS/MS analyses at serine residues 442, 444, and 44 in the C terminus of MAVS, which are phosphorylated by TBK1 and IKKβ upon viral infection." (PMID 32117959, 2020). "GSK-3β binds to TBK1 and enhances TBK1 activity by facilitating its auto-phosphorylation at Ser172 during viral infection, which then up-regulates type I IFN responses." (PMID 32849638, 2020). "The importance of the adaptor proteins TRIF, RIG-I, TBK1 and MyD88 in the pathogenesis of viral infections has been well established." (PMID 33335135, 2020). "During viral infection, K63-linked polyubiquitination of TRAF3 leads to the recruitment of TBK1-IKKε and subsequent activation of IRF3." (PMID 32562145, 2020).
viral infection (continued). "Upon viral infection, cellular TBK1- and IKKi-mediated phosphorylation of serines 385 and 386 and the serine/threonine cluster between amino acids 396 and 405 of IRF3 lead to its conformational change and activation." (PMID 33391252, 2020). "For instance, glycogen synthase kinase 3β physiologically binds to TBK1, facilitates TBK1 auto-phosphorylation at Ser172, leading to its kinase activation loop and activating TBK1 upon viral infection." (PMID 33584728, 2020). "Collectively, our study highlights PGAM5 as an important regulator for IFNβ production mediated via the TBK1/IRF3 signaling pathway in response to viral infection." (PMID 32433485, 2020). "It has been shown that SEC5 associates with phagosomes involved in the uptake of Staphylococcus aureus, and it is also involved in Tank-binding kinase 1 (TBK1)-dependent type I interferon innate immune responses against viral infections." (PMID 29703257, 2018). "TBK1 is a pivotal player in the production of type-I IFNs as the genetic ablation of TBK1 has a strong influence on type-I IFN induction after viral infection." (PMID 29755463, 2018). "In response to viral infection or to cytoplasmic double-stranded DNA, it was found that TBK1 activation was dependent on its interaction with TANK." (PMID 30223576, 2018). "SEC5 has been shown to modulate the TBK1-IRF-3 signaling-dependent type I interferon responses against viral infections." (PMID 29703257, 2018). "IRF3 is recruited to MAVS polymers through phosphorylation of two conserved serine and threonine clusters in MAVS by IKKs or TBK1 upon virus infection." (PMID 29125880, 2017). "Here, we showed that ERRα was specifically stabilized in response to the virus infection downstream of TBK1." (PMID 28591144, 2017). "Mechanistically, viral infection induced TBK1-dependent ERRα stabilization, which in turn increased its binding to TBK1 and IRF3 to prevent the formation of a functional TBK1-IRF3 complex." (PMID 28591144, 2017). "TBK1 null fibroblasts exhibited normal NF-κB activation in response to tumor necrosis factor α (TNFα), interleukin-1 and virus infection." (PMID 28493975, 2017). "Recent studies revealed that DDX3 participates in innate immune response during virus infection by interacting with TBK1 and regulating the production of IFN-β." (PMID 28402257, 2017). "Biochemically, GPATCH3 was recruited to VISA in a viral infection dependent manner where it disrupts the assembly of VISA/TRAF6/TBK1 complexes." (PMID 28414768, 2017). "In contrast, upon viral infection, the recruitment of TRAF6 and TBK1 to VISA was enhanced in GPATCH3 deficient cells." (PMID 28414768, 2017). "After viral infection and the stimulation of some pattern-recognition receptors, TANK-binding kinase I (TBK1) is activated by K63-linked polyubiquitination followed by trans-autophosphorylation." (PMID 27538435, 2016). "We now demonstrated that enhancement of TBK1 activity during the G2/M phase leads to increased IFN/ISG axis independently of viral infection." (PMID 25923723, 2015). "Third, the interaction between DYRK2 and TBK1 was the strongest at twelve hours after viral infection under physiological conditions; the interaction subsequently gradually disappeared." (PMID 26407194, 2015). "Enhancement of TBK1 activity in G2/M synchronized cells should lead to increased IFN-B gene expression at this cell cycle phase independently of viral infection." (PMID 25923723, 2015). "Since multiple E3 ligases have been proposed to conjugate ubiquitin onto TBK1 during virus infection including TRAF3, Mind bomb and Nrdp1, it is possible that RNF11 (and the A20 complex) also blocks TBK1/IKKi interactions with Mind bomb and Nrdp1." (PMID 23308279, 2013). "Upon virus infection the transcription factor IRF3 is phosphorylated within its C-terminal domain by TBK1/IKKi to trigger its dimerization and nuclear localization." (PMID 23308279, 2013).
viral infection (continued). "NEMO contains two ubiquitin-binding domains, which are essential for the activation of IKK and TBK1 in response to virus infection." (PMID 23951545, 2013). "Consistent with this, we found DNA-PK and TBK1 localised to sites of DNA replication during virus infection." (PMID 23251783, 2012). "For instance, antiviral immune responses by production of type-I IFNs upon virus infection are regulated by TANK-binding kinase 1 (TBK1) and I-kB kinase ε (IKKi)." (PMID 23162545, 2012). "Following viral infection K69R and K154R reconstituted cells displayed reduced enzyme activity as monitored by either TBK1 or IRF3 phosphorylation." (PMID 23028469, 2012). "Wild type TBK1 and the K372R mutant inhibited viral replication while the K69R and K154R single mutants demonstrated weakened protection from viral infection compared to wild type TBK1." (PMID 23028469, 2012). "Using a microarray-derived gene expression signature of TBK1 in response virus infection or poly(I∶C) stimulation, we found that TBK1 activation was strictly dependent on the integrity of the TBK1/TANK interaction." (PMID 21931631, 2011). "In contrast, TBK-1 was completely dispensable for IFN-α/β responses to virus infection in mouse bone marrow derived macrophage (BMM), where IKKɛ was predominant." (PMID 21994610, 2010). "If this were the case it suggests that optineurin is the first TBK1 specific adaptor protein found to date and that the TBK1-optineurin complex regulates distinct aspects of the response to virus infection." (PMID 20174559, 2010). "This idea is supported by the fact that expression of IKKɛ can rescue IFNβ inducibility in response to virus infection in Tbk1−/− fibroblasts and bone marrow-derived macrophages." (PMID 21994600, 2010). "This implies that SVCV-P, along with its associated TBK1 and IRF3 complexes, might be targeted for autophagic degradation during viral infection, as aggregated proteins are frequently cleared by this pathway (39, –, 41)." (PMID 41363845, 2026). "Autosomal recessive (AR) TBK1 deficiency was first reported in 2021, in four patients homozygous for LOF mutations of TBK1 presenting systemic autoinflammation with no prior history of severe viral infection." (PMID 41608123, 2025). "TBK1 is known to activate STAT1 through IRF3/7 in response to viral infections." (PMID 39415484, 2025). "Furthermore, immunofluorescence confocal microscopy demonstrated efficient colocalization of Frk with TBK1 post-viral infection." (PMID 40012791, 2025). "Targeting specific regulators involved in modulating TBK1 PTMs could emerge as a potential therapeutic strategy for the management and prophylaxis of viral infections." (PMID 40012791, 2025). "Through direct interaction with TBK1, PRMT1 induces asymmetric methylation of TBK1 at the R54, R134, and R228 residues, increasing its oligomerization following viral infection and facilitating TBK1 phosphorylation, ultimately leading to increased production of type I interferons." (PMID 38970666, 2024). "Indeed, TBK1 knockout or deletion in mice and cells suppressed defense mechanisms against bacterial and viral infection." (PMID 39493293, 2024). "Additionally, the type I Interferon response initiated via the activation of Toll-like receptors is vital in limiting viral infections and, as many emerging studies show, is regulated at the Golgi by TBK1, situating Golgi in the first line of cell defense." (PMID 38612929, 2024). "Next, we examined the effect of PTK2B in regulating TBK1 activation during viral infection." (PMID 37989995, 2023). "To understand why patients with TBK1 kinase mutation but not TBK1 deletion suffer from hyper-susceptibility to viral infections, we aimed at comparing the type I IFN response of TBK1-deficient with that of TBK1-mutated monocytic cells." (PMID 36936901, 2023).